ATG7 (autophagy related 7)
Diseases named in the same sentence as ATG7 in open-access papers (continued):
Sharing a sentence is not in itself a finding about the gene and the disease.
multiple sclerosis (1 paper, 2025). A progressive autoimmune disorder affecting the central nervous system resulting in demyelination. "Furthermore, diminished Atg7 protein expression has been observed in PBMCs from multiple sclerosis patients and spinal cords from animals with autoimmune encephalomyelitis, suggesting the involvement of Atg7 in immune‐related disorders." (PMID 40887825, 2025).
Myelodysplasia (1 paper, 2025). Clonal hematopoietic stem cell disorders characterized by dysplasia (ineffective production) in one or more hematopoietic cell lineages, leading to anemia and cytopenia. "This is consistent with previous research in a murine model of myelodysplasia showing a significant decrease in the expression of p-ATG1, p-ATG6, ATG7, and ATG12." (PMID 40728989, 2025).
Myocardial fibrosis (1 paper, 2025). "Subsequent histological analyses via HE staining and Masson trichrome staining revealed that METTL3-CKO mice showed greater survival of cardiomyocytes and reduced myocardial fibrosis compared to controls, with these effects reversed upon ATG7 knockdown." (PMID 39893158, 2025).
ocular toxoplasmosis (1 paper, 2010). Ocular toxoplasmosis is an infection in the eye caused by the parasite, Toxoplasm a gondii. "Moreover, mice with diminished expression of Beclin 1 and mice with inactivation of Atg7 in microglia/macrophages are susceptible to cerebral and ocular toxoplasmosis despite upregulation of IFN-γ, TNF-α and NOS2 as well as the induction of T cell-mediated immunity." (PMID 21217818, 2010). "Autophagy-deficient Beclin 1+/− mice, mice with deficiency of the autophagy protein Atg7 targeted to microglia/macrophages as well as CD40−/− mice exhibited impaired killing of T. gondii and were susceptible to cerebral and ocular toxoplasmosis." (PMID 21217818, 2010).
oligodendroglioma (1 paper, 2021). A well-differentiated (WHO grade II), diffusely infiltrating neuroglial tumor, typically located in the cerebral hemispheres. "Out of 21 oligodendrogliomas, ATG7 immunoexpression was high in 17/21 cases (81%) and low in 4/21 cases (19%); no staining for ATG4 was found in oligodendrogliomas." (PMID 33925821, 2021). "In particular, we tested ATG7 and ATG4 on the whole cohort of GBM and oligodendroglioma cases." (PMID 33925821, 2021).
oral cancer (1 paper, 2022). "Moreover, increased expressions of Beclin-1, Atg3, Atg5, Atg7, Atg12, Atg 16, LC3-I, and LC3-II proteins indicated that 4-carbomethoxyl-10-epigyrosanoldie E triggered autophagy in oral cancer cells." (PMID 36275891, 2022).
Osteoblastoma (1 paper, 2013). A rare benign bone-forming neoplasm usually arising from the spine. "The autophagy induction was also seen in salinomycin-treated MG-63 osteoblastoma cells, as the number of LC3B puncta positive cells and expressions of beclin-1/LC3B-II /ATG-7 were increased after salinomycin stimulation." (PMID 24358342, 2013).
ovarian insufficiency (1 paper, 2021). "Functional analysis showed that autophagy contributes to mouse oogenesis, since germ cell specific Atg7 deletion resulted in ovarian insufficiency and subfertility." (PMID 34204653, 2021). "This complex phenotype of Atg7 null females resembles the primary ovarian insufficiency in women aged <40 years and therefore could become an interesting animal model for this age-dependent human syndrome." (PMID 34204653, 2021).
pancreatic insufficiency (1 paper, 2022).
parasite infection (1 paper, 2023). "Cytoprotective autophagy genes, ATG5 and ATG7, are known to be upregulated as a result of PERK/ATF4 pathway activation, which favors cellular survival and parasite infection." (PMID 37152895, 2023).
peripheral nerve injury (1 paper, 2025). Injury to a peripheral nerve. "Furthermore, METTL3-mediated maturation of miR-192-5p, which targets autophagy-related 7 (Atg7), was found to prevent Schwann cell autophagy during peripheral nerve injury." (PMID 40508158, 2025).
pigmentation diseases (1 paper, 2020). "In that case, alteration of ATG7-dependent autophagy might be involved in the pathogenesis of pigmentation diseases owing to its impact on melanogenesis." (PMID 32377394, 2020).
pneumonia (1 paper, 2025). An acute, acute and chronic, or chronic inflammation focally or diffusely affecting the lung parenchyma, caused by an infection in one or both of the lungs (by bacteria, viruses, fungi, or mycoplasma.). "Our investigation used a PCR-DNA-sequencing procedure to illustrate the difference in immunological (IL-1α, IL1B, IL6, TNF-α, IL10, and IFN-γ) and antioxidant (PRDX6, ATG7, NDUFS6, and NOX4) genes in calves with pneumonia and healthy calves." (PMID 40711280, 2025).
polycystic kidney disease (1 paper, 2025). A usually autosomal dominant and less frequently autosomal recessive genetic disorder characterized by the presence of numerous cysts in the kidneys leading to end-stage renal failure. "A common feature of Atg7−/− kidneys, polycystic kidneys, and ischemic kidneys was p-S6 staining in the tubules in close proximity to TLTs." (PMID 40496859, 2025). "The aim of the study was to determine the mechanistic role of mTORC1 in TLT formation and growth, using pharmacological and genetic techniques, in Atg7 knockout kidneys and in two common models of kidney disease, polycystic kidney disease (PKD) and kidney ischemia." (PMID 40496859, 2025).
Pompe disease (1 paper, 2013). "The only previous analyses of the Atg genes and glycogen autophagy was in the mouse Pompe disease model, and was limited to mutations in two genes, Atg7 and Atg5, which surprisingly had different effects on the amount of lysosmal glycogen." (PMID 24265594, 2013). "The only in vivo genetic analysis of the role of these systems during glycogen transport to the lysosome was performed in the mouse model of Pompe disease, where glycogen accumulation in the lysosome was diminished in Atg7-deficient GAA KO muscles." (PMID 24265594, 2013).
preeclampsia (1 paper, 2022). Preeclampsia is a hypertensive disorder of pregnancy that is characterized by new-onset hypertension with proteinuria presenting after 20 weeks of gestation, and depending on mild or severe forms may initially present with severe headache, visual disturbances, and hyperreflexia. "Furthermore, the ATG7 knockout placentas were featured with shallow trophoblast invasion and defective vascular remodelling, both of which are the characteristics of the placenta in preeclampsia." (PMID 36090032, 2022).
presbycusis (1 paper, 2022). Bilateral hearing loss caused by progressive degeneration of cochlear structures and central auditory pathways, typically associated with the aging process. "In the PPI network, autophagy-related genes ATG5, ATG7 showed the highest node scores in mild presbycusis; whereas MTOR, BECN1 showed the highest scores in severe presbycusis." (PMID 35463035, 2022).
primary ovarian insufficiency (1 paper, 2026). "Interestingly, several commonly upregulated genes were observed across cell types, including PTEN, TGFBR2, ATG7, and ESR1, which are implicated in primary ovarian insufficiency." (PMID 41243550, 2026).
Pulmonary hemorrhage (1 paper, 2021). Pulmonary hemorrhage is a bleeding within the lungs. "Our results demonstrate that loss of ATG7 in B cells reduced the susceptibility of mice to pristane-induced pulmonary hemorrhage." (PMID 34335611, 2021).
Renal insufficiency (1 paper, 2021). A reduction in the level of performance of the kidneys in areas of function comprising the concentration of urine, removal of wastes, the maintenance of electrolyte balance, homeostasis of blood pressure, and calcium metabolism. "Moreover, inhibiting autophagy in proximal convoluted tubules with chloroquine or knocking out autophagy gene-related 7 (Atg7) molecules led to tissue damage, renal insufficiency, and apoptosis." (PMID 35186974, 2021).
sarcoma (1 paper, 2021). A usually aggressive malignant neoplasm of the soft tissue or bone. "Since the overexpression of the autophagic genes ATG5 and ATG7 in sarcoma 180 cells was induced, we performed monodansylcadaverine staining to verify whether the formation of autophagic vacuoles was induced by the treatment with complex 1 at 1 μM, 4 μM and 20 μM." (PMID 34961767, 2021).
silicosis (1 paper, 2023). Silicosis is a respiratory disease caused by breathing in (inhaling) silica dust. "WB results showed that in the lung tissue of silicosis model mice, compared with the control group, SiO2 significantly increased the expression of the ATG7 protein in lung tissue; compared with the SiO2 group, Tet intervention further promoted the expression of ATG7." (PMID 37755775, 2023).
Simpson-Golabi-Behmel syndrome (1 paper, 2013). Simpson-Golabi-Behmel syndrome is a rare X-linked multiple congenital anomalies syndrome, characterized by pre- and postnatal overgrowth, distinctive craniofacial features, variable congenital malformations, organomegaly and an increased tumor risk. "In addition, blocking autophagy using small interfering RNA targeted to ATG7 in human Simpson-Golabi-Behmel syndrome adipocytes resulted in up-regulation of inflammatory marker." (PMID 23668414, 2013).
skin aging (1 paper, 2019). The gradual irreversible changes in structure of skin that occur as a result of the passage of time.. "Some researchers constructed a Drosophila model of skin aging and found that the increased expression of the autophagy marker, Atg7, was associated with skin aging." (PMID 31915506, 2019).
skin cancer (1 paper, 2022). "In summary, the deletion of Atg7 reduced the growth of epithelial tumors in these two mouse models of skin cancer." (PMID 36429119, 2022). "In the K5-SOS EGFRwa2/wa2 model of skin cancer, the inactivation of Atg7 was compatible with tumorigenesis in 8 out of 10 mice, but 2 mice did not develop tumors." (PMID 36429119, 2022). "To determine the role of autophagy in skin tumor formation, we first subjected epidermis-specific Atg7 knockout mice (Atg7Δep) and control littermates (Atg7f/f) to the DMBA/TPA protocol of skin carcinogenesis." (PMID 36429119, 2022). "Here, we investigated the role of autophagy in the initiation and progression of epithelial skin tumors by ablating Atg7 in two mouse models of skin cancer: DMBA/TPA-mediated two-stage carcinogenesis and genetically driven carcinogenesis in the K5-SOS EGFRwa2/wa2 model." (PMID 36429119, 2022).
Streptococcus infection (1 paper, 2018). "Atg7 conditional knockout mice succumbed either to Streptococcus infection shortly after Atg7 deletion or to neurodegeneration 2 to 3 months later." (PMID 30622432, 2018).
tauopathy (1 paper, 2012). Neurodegenerative disorders involving deposition of abnormal tau protein isoforms (tau proteins) in neurons and glial cells in the brain. "Although genetic mutations in ATG7 have not been described in human disease, mutations within other components of the macroautophagy-lysosomal pathway underlie tauopathies, consistent with our observations in the mouse model." (PMID 22998728, 2012). "However, the phospho-tau aggregates in the context of Atg7-deficient neurons do not replicate aspects of mature human tauopathy pathology." (PMID 22998728, 2012). "Phosphorylated tau was significantly accumulated in Atg7 cKO brains, but neurofibrillary tangles that typify end-stage human tauopathy were not apparent." (PMID 22998728, 2012). "Atg7 cKO in mouse forebrain neurons led to an age-dependent neurodegeneration with ubiquitin/p62-positive and phospho-tau/GSK3β inclusions, but not the full pathological features of NFTs in tauopathy." (PMID 22998728, 2012).
testicular cancer (1 paper, 2022). A primary or metastatic malignant neoplasm that affects the testis. "In addition, ATG7 was downregulated after miR-188-3p overexpression in the human testicular cancer cell line NTERA-2 and was upregulated after miR-188-3p inhibition." (PMID 35710416, 2022).
tongue cancer (1 paper, 2025). A malignant neoplasm affecting the tongue. "A substantial reduction in ATG7 gene expression following treatment with Rumex dentatus extract suggests that the extract may inhibit autophagy in tongue carcinoma cells." (PMID 39863836, 2025).
triple-negative breast carcinoma (1 paper, 2022). An invasive breast carcinoma which is negative for expression of estrogen receptor (ER), progesterone receptor (PR), and human epidermal growth factor receptor 2 (HER2). "In agreement with this study, ATG7 was shown to inhibit EMT in triple-negative breast cancer cells (TNBC) by upregulation of E-cadherin and downregulation of N-cadherin, SMA, and Vimentin." (PMID 40396019, 2022).
vascular tumor (1 paper, 2023). "To explore the mechanisms of autophagy in the regulation of vascular tumor cells, we examined changes in gene expression by transcriptional profiling of Fip200 KO, Atg5 KO, and Atg7 KO cells." (PMID 36813768, 2023).
ZIKV infection (1 paper, 2020). "Besides, specific siRNA strategy confirmed that autophagy can be activated through Atg7-Atg5 and type I IFN signaling pathway upon ZIKV infection, while knocking down of Atg7 and Atg5 effectively decreased the ZIKV clearance in phagocytes." (PMID 32410874, 2020).
tumor (280 papers, 2011 to 2026). "Its evidence is present when autophagy-associated proteins like ATG5, ATG7, and Beclin-1 are impaired, and then spontaneous tumors are reported, suggesting their tumor suppressive function." (PMID 40444035, 2025). "Dietary supplementation of Atg7-deficient hosts with Arg partially restored levels of circulating Arg and tumor growth." (PMID 41249150, 2025). "We showed that Atg7 was required for both tumor initiation and intestinal tumor cell metabolism and that the loss of Atg7 in IEC prevents tumor initiation by shaping an antitumoral immune response linked to a change in the composition of the microbiota." (PMID 39971913, 2025). "Accordingly, rescuing the autophagy deficiency of clone A by overexpression of Atg7 gene shifts the role of Atg5 from pro‐tumor to anti‐tumor status, indicating the dual role of Atg5 in tumorigenesis." (PMID 38826147, 2024). "Tumor (Tum) and non‐tumor (NTum) tissue was harvested from 9 months old Atg7 deficient mice to analyze the proteomic profile." (PMID 39284785, 2024). "The study further demonstrated that tumor growth inhibition in Atg7‐deficient hosts is STING‐dependent." (PMID 38506049, 2024). "Intestinal dysbiosis is caused by a deficiency of Atg7, which in turn inhibits tumor development via an immunological response controlled by the microbiome." (PMID 37108476, 2023). "Dietary arginine supplementation in Atg7-deficient hosts partially restores circulating arginine levels and tumor growth, thus revealing a novel metabolic vulnerability in cancer from an autophagic defect in the host." (PMID 38067169, 2023). "A deficiency of Atg7 in BrafV600E/+ and Pten+/Δ; BrafV600E/+-driven melanoma mice decreased tumor growth and increased survival." (PMID 38067169, 2023). "In the azoxymethane (AOM)/DSS-induced CRC model in vitro and in sporadic CRC, the inhibition of tumor growth was also demonstrated by a loss of ATG7 (exclusion of autophagy)." (PMID 36835075, 2023). "We directly demonstrated that a somatic deletion of the ATG7 wildtype allele in an affected tumor sample represented a second hit event." (PMID 35725745, 2022). "This causes its binding to Atg7, the E1-like protein, leading to cancer cell death via autophagy and tumor suppression." (PMID 35629968, 2022). "In contrast to the tumour suppressive effect of ATG7 on tumour development, blockage by ATG7 deficiency contributed to promoting the sensitivity to chemotherapy in resistant cells." (PMID 35690866, 2022). "A similar result was observed in KRAS-driven cancer cell lines where the antiproliferative effects of CQ were similar between ATG7-deficient tumor cell lines with undetectable autophagic flux and ATG7-efficient tumor cell lines." (PMID 33718194, 2021). "Studies showing mouse survival with ATG7 deficiency in prostrate tumor and intestinal cancer suggest that autophagy helps in tumor progression." (PMID 33628386, 2021). "Compared to ATG7-deficient liver, combined p62 and autophagy loss in Atg7−/− liver abrogate inclusion body formation, alleviate hepatic injury, and retard tumor progression." (PMID 33628386, 2021). "Early reported shown that autophagy-deficient Ras-driven NSCLC mouse have reduced its tumor malignancy and growth capacity, and Atg7-deficient tumors have more active apoptosis and immune response level." (PMID 34823534, 2021). "Tumour analysis revealed somatic loss of ATG7 affecting several family members, providing a strong link between cancer formation and ATG7 dysfunction." (PMID 34725936, 2021). "Deletion of ATG5 and ATG7, increased p62 expression, mitochondrial swelling, oxidative stress, and genomic damage in primary hepatocytes and deletion of the p62 gene reduced tumor size in ATG7 deficiency liver tumors." (PMID 33976943, 2021).